FRMD7 (FERM domain containing 7)
Description:
Plays a role in neurite development, may be through the activation of the GTPase RAC1. Plays a role in the control of eye movement and gaze stability.
Synonyms: FLJ43346; NYS; NYS1; XIPAN
Tractability: Antibody: its Gene Ontology location is reachable by antibodies, with high confidence; the Human Protein Atlas places it where antibodies can reach. PROTAC: ubiquitination databases record sites on it.
Gene: Protein-coding gene on chromosome X (132,076,990 to 132,128,020, reverse strand). Ensembl gene ENSG00000165694.
Subcellular location: Cell projection, neuron projection; Cell projection, growth cone
Subcellular location (Human Protein Atlas): Plasma membrane; Cytosol; Nucleoplasm
Gene Ontology:
Molecular function: protein binding; guanyl-nucleotide exchange factor activity
Biological process: regulation of neuron projection development
Cellular component: extracellular region; growth cone; neuron projection; neuronal cell body
Homologues: Orthologues: chimpanzee FRMD7 (99% identical), macaque FRMD7 (96% identical), rabbit FRMD7 (91% identical), pig FRMD7 (88% identical), guinea pig FRMD7 (88% identical), rat Frmd7 (85% identical), mouse Frmd7 (85% identical), chimpanzee FRMD7 (82% identical), dog FRMD7 (72% identical), zebrafish frmd7 (40% identical), tropical clawed frog frmd7 (34% identical), Caenorhabditis elegans frm-3 (29% identical), and 2 more. Paralogues in human: FARP1 (39% identical), FARP2 (34% identical), FGD6 (11% identical), FGD5 (10% identical), ECT2L (8% identical), FGD4 (7% identical), FGD1 (7% identical), FGD3 (6% identical), FGD2 (5% identical), ARHGEF39 (4% identical).
Diseases named in the same sentence as FRMD7 in open-access papers:
FRMD7 is named in the same sentence as 20 diseases in open-access papers, as found by Europe PMC text mining. Sharing a sentence is not in itself a finding about the gene and the disease. The quoted sentences say what the papers report.
Nystagmus (29 papers, 2008 to 2024). Rhythmic, involuntary oscillations of one or both eyes related to abnormality in fixation, conjugate gaze, or vestibular mechanisms. "Our identification of two mutations in the FRMD7 gene, leading to nystagmus in two families, is of great significance." (PMID 38279119, 2024). "The FERM protein family includes a large number of proteins and, interestingly, another member of this protein family, FRMD7, is associated with nystagmus." (PMID 39583022, 2024). "Mutations associated with nystagmus in FRMD7 are highly clustered in the N-terminal region of the protein, strongly suggesting that the FERM and FA structural domains are important for the normal function of FRMD7 protein." (PMID 38279119, 2024). "More than half of the mutant phenotypes of FRMD7 cause the appearance of nystagmus symptoms, and 1/3 are associated with idiopathic nystagmus in infants." (PMID 38279119, 2024). "Horizontal direction selectivity is dependent on the FRM domain protein FRMD7, a protein implicated in human nystagmus." (PMID 35021080, 2022). "We report a novel FRMD7 variant herein, expanding the already known gene mutation spectrum of idiopathic infantile nystagmus." (PMID 36072665, 2022). "The hemizygous FRMD7 c.910C > T (p.R304X) mutation led to Nystagmus of the boy in Family 41, and his mother was a heterozygous carrier of the mutation." (PMID 33781268, 2021). "Herein, FRMD7 mutation was established in iNs which mimics the cell model of congenital nystagmus caused by FRMD7 mutation, it made more favorable confirmation of the role for FRMD7 mutation on neuronal processes and maturation." (PMID 31743612, 2019). "Recently, mutations in FRMD7 were found to be responsible for X-linked infantile nystagmus [8-10, 11,]." (PMID 18431453, 2008). "Considering that 80% of mutations in exon 12 are frameshift mutations that generate abnormal FRMD7 protein function, mutations at this location may lead to more severe nystagmus." (PMID 38279119, 2024). "The loss of FRMD7 protein may lead to mild nystagmus due to haploinsufficiency, only the production of additional harmful truncated proteins and the generation of additional abnormal protein functions will result in severe nystagmus." (PMID 38279119, 2024). "Individuals depicting the nystagmus phenotype associated with mutations in the FRMD7 gene are broadly characterized under the term FRMD7-related infantile nystagmus or FIN, which is characterized by the presence of horizontal, gaze-dependent congenital nystagmus." (PMID 36833273, 2023). "Further studies are needed to determine how FRMD7 mutations lead to the abnormal developments of afferent systems, and subsequent effects on the neural circuit within the oculomotor system generating nystagmus." (PMID 26268155, 2015). "This study shows for the first time that abnormal afferent system development is associated with FRMD7 mutations and could be an important etiological factor in the development of nystagmus." (PMID 24688117, 2014). "Abnormal motion selectivity in retina in mice due to altered organization of neural networks caused by FRMD7 mutations also raises the possibility that nystagmus could be driven by abnormal inputs from the retina rather than as high gain oculomotor response to reduced inputs." (PMID 35616929, 2022). "Thus, FRMD7 mutation may cause nystagmus by damaging neuronal activity in the area of the brain that controls eye movement." (PMID 30616528, 2019). "Thus, FRMD7 mutations may cause nystagmus by defective axogenesis, dendritogenesis, and neuronal guidance in the areas of the brain that control eye movements." (PMID 26268155, 2015). "Equally, loci associated with foveal hypoplasia, nystagmus and hypopigmentation (AHR, FRMD7, GPR143, and SLC38A8) were assessed for SNV or SV segregating with disease." (PMID 38383453, 2024).
Nystagmus (continued). "In this study, we have explored the potential advantages of this Frmd7 knock-out mouse model to further characterize Frmd7 expression patterns and function in order to study human FRMD7 mutant nystagmus." (PMID 33007925, 2020). "Expression of the nystagmus-related FRMD7 protein was examined during three stages of human fetal development (16–17, 21, and 25 wpc) and in five different regions (cortex, brainstem, hippocampus, cerebellum, and diencephalons) for each stage." (PMID 21386928, 2011). "The purpose of this study is to investigate FRMD7 gene mutations in patients with IN, and to evaluate the nystagmus intensity among patients with and without FRMD7 mutations." (PMID 35705619, 2022). "The parameters of nystagmus intensity and the patients’ best corrected visual acuity were not statistically different among the patients with and without identified FRMD7 mutations, and also not different among patients with different mutant types." (PMID 35705619, 2022). "Although the variant p.Tyr457fs identified in our study is far from the two important domains known, the truncated protein may destroy the function of FRMD7, which led to the manifestations of nystagmus in the family." (PMID 31495972, 2020). "We also demonstrated abnormal developments of afferent system in patients with FRMD7 mutations using OCT, which may help to understand an etiological factor in development of nystagmus." (PMID 26268155, 2015). "We also demonstrated abnormal developments of afferent system in patients with FRMD7 mutations using OCT, which may help to understand the etiological factor in development of nystagmus." (PMID 26268155, 2015). "Recently, it has been shown that CASK recruits FRMD7 to the plasma membrane to promote neurite outgrowth during development of the oculomotor neural network and disruption of this interaction results in nystagmus." (PMID 24688117, 2014). "No mutations were found in FRMD7 gene (MIM 300628) involved in the pathogenesis of the nystagmus of the child." (PMID 25478008, 2014). "Nystagmus may be a symptom of an X-linked disorder caused by the loss of one of the sex chromosomes, specifically a change in the FRMD7 gene; this disorder does not usually affect female individuals." (PMID 39336938, 2024). "Additionally, our conjecture suggests that the loss of FRMD7 protein function might not solely drive pathology; rather, the emergence of aberrant protein function could be pivotal in nystagmus etiology." (PMID 38279119, 2024). "However, the conclusion that congenital nystagmus arises as a consequence of a mere absence of the OKR is unwarranted, since, for example, mice with mutations in FERM domain-containing protein 7 (FRMD7) have no horizontal OKR but do not develop a pathological nystagmus." (PMID 31513577, 2019). "The key factor is X chromosome inactivation.The proband’s mother in this study had high myopia without nystagmus,which suggests that the variation in the FRMD7 gene is responsible for high myopia." (PMID 37749571, 2023). "Affected males with or without FRMD7 mutations were collected to compare the difference between the best corrected visual acuity (BCVA) and nystagmus intensity because the affected males were hemizygote and carried only one affected allele on the X-chromosome." (PMID 35705619, 2022). "However, a recent study found that mutations within the C-terminal region of CASK disrupt the interaction, which is crucial for correct development of oculomotor control between FRMD7 and CASK, leading to nystagmus." (PMID 33732697, 2021). "We observed no spontaneous oscillatory eye movements (nystagmus) in both the Frmd7.tm1a Frmd7.tm1b mice." (PMID 33007925, 2020). "Unlike other forms of nystagmus, CIN is widely associated with mutations in the FRMD7 gene." (PMID 36833273, 2023).
congenital nystagmus (24 papers, 2008 to 2025). Nystagmus present at birth or caused by lesions sustained in utero or at the time of birth. "The strongest evidence for this was in the investigation of FRMD7, a gene that is associated with congenital nystagmus when mutated." (PMID 38514178, 2024). "Mutations in the genes coding for GPR143 and FERM domain-containing 7 (FRMD7), both found on the X-chromosome, have been linked to congenital nystagmus, one of features of ocular albinism that can occur as a non-syndromic condition." (PMID 35495622, 2022). "Such an approach has led us to identify the circuit mechanism in a common human neurodevelopmental disease: FRMD7 gene‐associated congenital nystagmus." (PMID 30670464, 2019). "We showed that mutation of FRMD7, a gene that is defective in human congenital nystagmus, leads to selective loss of the horizontal optokinetic reflex in mice, as it does in humans." (PMID 30670464, 2019). "Mutations in the FERM domain–containing 7 (FRMD7) gene are responsible for the X-linked congenital idiopathic nystagmus." (PMID 26160353, 2015). "In conclusion, nearly half a century after the first report on an enigmatic association of congenital nystagmus and central hypothyroidism, we identified a male newborn with the same association and a Xq26 deletion encompassing FRMD7 and IGSF1." (PMID 25780367, 2015). "In other studies, mutations in FRMD7 were identified in families that were affected with X-linked congenital nystagmus." (PMID 22262942, 2012). "Mutations of the FERM domain containing protein 7 (FRMD7) gene are known to be one of the main causes of X-linked idiopathic congenital nystagmus." (PMID 22690121, 2012). "In this study, we identified a novel splice-site mutation, c.163–1G→T, in FRMD7 of a Chinese family that has X-linked congenital nystagmus." (PMID 22262942, 2012). "Mutations of the FERM domain containing protein 7 gene (FRMD7) are associated with X-linked idiopathic congenital nystagmus." (PMID 22690121, 2012). "Approximately 44 mutations causing congenital nystagmus have been reported in FRMD7, including 23 missense mutations, 8 splicing site mutations, 1 synonymous mutation, 4 nonsense mutations, 6 frame-shift mutations, and 2 deletions." (PMID 22065930, 2011). "To date, 40 mutations in FRMD7 have been reported worldwide in families with X-linked congenital nystagmus from various ethnic backgrounds." (PMID 21365021, 2011). "Further biochemical studies of the mutations in FRMD7 will yield insight into its molecular mechanism underlying the pathogenesis of congenital idiopathic nystagmus." (PMID 18431453, 2008). "We identified a novel mutation in FRMD7 and confirmed the role of this mutation in the pathogenesis of X-linked congenital nystagmus." (PMID 18246032, 2008). "To show how EyeLoop may be applied to these ends, we confirmed previous findings showing that Frmd7 hypomorphic mice lack the horizontal optokinetic reflex; similar to Frmd7-mutated congenital nystagmus patients." (PMID 34955752, 2021). "FRMD7 maps to Xq26.2 and is associated with X-linked idiopathic congenital nystagmus." (PMID 23613933, 2013). "Our data expands the mutation spectrum of FRMD7 in causing congenital nystagmus and may be helpful for understanding the molecular pathogenesis of XLCN." (PMID 22262942, 2012). "Direct sequencing of FRMD7 could be used as a diagnostic testing of idiopathic congenital nystagmus." (PMID 22065930, 2011). "As the Rac1 signaling pathway appears to be involved in the regulation of neurite extension in the developmental stage, mutations of the FRMD7 gene which alter the regulation of Rac1 signaling may be linked to the pathogenesis of idiopathic congenital nystagmus." (PMID 23967341, 2013). "X-linked IIN (XLIIN) is the most common form of congenital nystagmus, and the FERM domain-containing gene (FRMD7) is the most common cause of pathogenesis, followed by mutations in GPR143." (PMID 37545716, 2023).
congenital nystagmus (continued). "For the molecular diagnosis of this pedigree, the FRMD7 gene (candidate gene for congenital nystagmus) and GPR143 gene (candidate gene for OA1) were analyzed." (PMID 22916221, 2012). "Direct sequencing of FRMD7 can be used as a method in gene diagnosis of idiopathic congenital nystagmus." (PMID 22065930, 2011). "Idiopathic congenital nystagmus (ICN) is an ocular movement disorder and X-linked inheritance mode is more common, accounting for about 90% of cases, and the main pathogenic genes are FRMD7 and GPR143, with variants in the FRMD7 gene being more common." (PMID 37749571, 2023). "Another gene, FRMD7, involved in the development of congenital nystagmus, was screened and no mutation was found." (PMID 22916221, 2012).
albinism (10 papers, 2014 to 2023). A congenital disorder characterized by partial or complete absence of melanin pigment in the eyes, hair, or skin. "Similar but milder structural and functional abnormal retinal development in IIN, as found in albinism, has been shown in association with FRMD7 mutations." (PMID 35616929, 2022). "Panel testing confirmed a FRMD7 hemizygous mutation causing X-linked congenital nystagmus in one family with suspected albinism, where the VEP was inconclusive." (PMID 33808351, 2021). "The periodicity and features of PAN we describe in F8:II-1 are similar to what has been documented with albinism and FRMD7 mutations." (PMID 32744312, 2020). "Typically, patients with FRMD7 mutations tend to have better visual acuity compared with patients with albinism." (PMID 24688117, 2014). "Infantile nystagmus (IN) may result from aetiologies including albinism and FRMD7 mutations." (PMID 33531592, 2021). "A multicentre study of 907 patients with FH found that 67% of individuals had albinism caused by variants in GPR143, OCA2, TYR and HPS1 genes, followed by 21.8% with PAX6, 6.8% with SLC38A8 and 3.5% with FRMD7 variants." (PMID 37762234, 2023). "FH has been described in various ocular conditions, including albinism, mutations in genes such as SCLC38A8, PAX6, FRMD7 and AHR and achromatopsia." (PMID 37762234, 2023). "Six were congenital cataracts, 10 patients were anterior-segment dysgenesis including PAX6-related phenotype, 48 were retinal dystrophy, and 85 were neuro-ophthalmic condition such as optic atrophy, albinism, or FRMD7-related infantile nystagmus." (PMID 35052368, 2021). "The genes identified for MAC were KMT2D, MAB2IL2, ALDH1A3; ASDA were KERA, PAX6, MYOC, TGFBI, and SLC4A11; congenital cataract were CRYBB2, EPHA2, HSF4 and BCOR; infantile nystagmus were CACNA1A and FRMD7; and albinism were OCA2, GPR143, HPS6 and SLC38A8." (PMID 32830442, 2020).
neuroblastoma (7 papers, 2011 to 2024). Neuroblastoma (NB) is the most common solid, extracranial childhood tumor. "Enhanced green fluorescent protein (EGFP)-tagged recombinant plasmids DNA encoding the normal or mutant FRMD7 were used to transiently transfect the mouse neuroblastoma cells (Neuro-2a) and human embryonic kidney 293 cells (HEK293T)." (PMID 21386928, 2011). "They found that FRMD7 expression was upregulated in retinoic acid (RA)-induced adult neuroblastoma in differentiating NEURO2A cells in mice." (PMID 38279119, 2024). "FRMD7 has been shown to regulate neuronal outgrowth by influencing the dynamics of F-actin during retinoic acid-induced differentiation in mouse neuroblastoma cells." (PMID 30616528, 2019). "Our study used quantitative real-time PCR to assess the levels of neuron-specific genes in a mouse neuroblastoma cell line (Neuro-2a) after transfection with a full-length coding transcript of FRMD7 or a blank control vector." (PMID 22690121, 2012). "The COOH-terminus of FRMD7 was found to play a key role in the subcellular localization of FRMD7 in mouse neuroblastoma cells (Neuro-2a) and human embryonic kidney 293 cells (HEK293T)." (PMID 21386928, 2011). "In-vivo studies to determine FRMD7 interactions have revealed it to be involved in promoting mouse neuroblastoma cell growth by being involved with calcium/calmodulin-dependent serine protein kinases (CASK), which is suggestive of its association with the development of the retina and neural cells." (PMID 36833273, 2023). "FRMD7 downregulation has been shown to alter the development of neurites by influencing the dynamics of F-actin during retinoic acid (RA)-induced differentiation in mouse neuroblastoma (Neuro-2a) cells." (PMID 23967341, 2013). "Studies depicting an increased expression of the FRMD7 gene during retinoic acid (A)-induced differentiation of mouse neuroblastoma cells suggest that FRMD7 may play a part in neuronal processes as well; however, further research is required to validate FRMD7’s role in development." (PMID 36833273, 2023). "Here, we demonstrate that the full length of the mouse FRMD7, rather than the N-terminus or the C-terminus alone, directly interacts with RhoGDIα and specifically initiates Rac1 signaling in mouse neuroblastoma cell line (neuro-2a)." (PMID 23967341, 2013).
Idiopathic infantile nystagmus (5 papers, 2014 to 2023). "Idiopathic infantile nystagmus (IIN) is a high genetically heterogeneous ophthalmic disease and is often associated with pathogenic mutations in FRMD7 and GPR143, respectively." (PMID 31495972, 2020). "Idiopathic infantile nystagmus (IIN) is a genetically heterogeneous disorder, often associated with FRMD7 mutations." (PMID 24688117, 2014). "Idiopathic infantile nystagmus (IIN) is an inherited disorder occurring in the first 6 months of life, with no underlying retinal or neurological etiologies and is predominantly caused by mutations in the FRMD7 gene." (PMID 36072665, 2022).
congenital cataracts (3 papers, 2019 to 2021). "This is the first time that FRMD7 and GJA8 gene mutations have been linked to the pathogenesis of a family with both CN and congenital cataracts." (PMID 30890130, 2019). "Mutations in FRMD7 and GJA8 genes were responsible for the pathogenesis of CN and congenital cataracts respectively." (PMID 30890130, 2019).
Turner syndrome (2 papers, 2023 to 2024). Turner syndrome is a chromosomal disorder associated with the complete or partial absence of an X chromosome. "Here we report the first case of a patient with Turner syndrome and INN in an XLIIN pedigree, in which we identified a novel frameshift mutation (c.1492dupT) in the FRMD7 gene: the absence of one X chromosome in the patient unmasked the presence of the familial genetic nystagmus." (PMID 37545716, 2023).